SLC25A13 (solute carrier family 25 member 13)
Description:
Mitochondrial electrogenic aspartate/glutamate antiporter that favors efflux of aspartate and entry of glutamate and proton within the mitochondria as part of the malate-aspartate shuttle. Substrate exchange across the membrane occurs consecutively with one substrate being transported first, then dissociating from the substrate binding site before the second substrate binds for transport in the opposite direction. Also mediates the uptake of L-cysteinesulfinate (3-sulfino-L-alanine) by mitochondria in exchange for L-glutamate and proton. Can also exchange L-cysteinesulfinate with aspartate in their anionic form without any proton translocation. Lacks transport activity towards gamma-aminobutyric acid (GABA).
Synonyms: ARALAR2; CITRIN; CTLN2; NICCD
Tractability: Antibody: UniProt predicts a signal peptide or a membrane-spanning region. PROTAC: ubiquitination databases record sites on it; its protein half-life has been measured.
Gene: Protein-coding gene on chromosome 7 (96,120,218 to 96,322,147, reverse strand). Ensembl gene ENSG00000004864.
Subcellular location: Mitochondrion inner membrane
Subcellular location (Human Protein Atlas): Mitochondria
Pathways (Reactome):
Metabolism: Aspartate and asparagine metabolism; Malate-aspartate shuttle
Protein localization: Mitochondrial protein import
Gene Ontology:
Molecular function: 3-sulfino-L-alanine: proton, glutamate antiporter activity; aspartate:glutamate, proton antiporter activity; calcium ion binding; identical protein binding; protein binding; L-aspartate transmembrane transporter activity; L-glutamate transmembrane transporter activity; acidic amino acid transmembrane transporter activity
Biological process: aspartate transmembrane transport; ATP biosynthetic process; cellular respiration; L-glutamate transmembrane transport; malate-aspartate shuttle; response to calcium ion; mitochondrial transport; gluconeogenesis; L-aspartate transmembrane transport; neutral amino acid transport; proton transmembrane transport; transmembrane transport
Cellular component: mitochondrial inner membrane; mitochondrion; plasma membrane
Genetic constraint (gnomAD): Loss-of-function variants: 68 observed, 88.79 expected, observed/expected ratio (o/e) 0.77, 90% interval 0.63 to 0.94. The upper end of that interval is the gene's LOEUF score, 0.94, which puts it in group 3 of 6, group 1 being the genes least tolerant of losing a copy. Missense variants: 761 observed, 853.25 expected, observed/expected ratio (o/e) 0.89, 90% interval 0.84 to 0.95. Synonymous variants: 257 observed, 303.87 expected, observed/expected ratio (o/e) 0.85, 90% interval 0.76 to 0.94.
Gene-disease validity (ClinGen):
ClinGen rates the evidence that SLC25A13 causes each of these diseases.
citrin deficiency (autosomal recessive): Definitive.
Homologues: Orthologues: chimpanzee SLC25A13 (100% identical), macaque SLC25A13 (99% identical), dog SLC25A13 (97% identical), guinea pig SLC25A13 (97% identical), pig SLC25A13 (96% identical), rat Slc25a13 (96% identical), mouse Slc25a13 (96% identical), rabbit SLC25A13 (94% identical), tropical clawed frog slc25a13 (87% identical), zebrafish slc25a13 (74% identical). Paralogues in human: SLC25A12 (77% identical), SLC25A25 (17% identical), SLC25A24 (16% identical), SLC25A23 (16% identical), SLC25A22 (15% identical), SLC25A28 (14% identical), SLC25A29 (14% identical), SLC25A20 (14% identical), UCP2 (14% identical), SLC25A18 (14% identical), SLC25A21 (14% identical), SLC25A6 (14% identical), and 37 more.
Diseases named in the same sentence as SLC25A13 in open-access papers:
SLC25A13 is named in the same sentence as 81 diseases in open-access papers, as found by Europe PMC text mining. Sharing a sentence is not in itself a finding about the gene and the disease. The quoted sentences say what the papers report.
citrin deficiency (47 papers, 2012 to 2026). "Citrin deficiency (CD) is now recognised as an autosomal recessive disorder caused by mutations in the SLC25A13 gene, which encodes citrin, a protein located in the inner mitochondrial membrane." (PMID 40947814, 2025). "The genetic studies elucidated that the underlying cause of Citrin deficiency is due to the mutation in SLC25A13-a mitochondrial localized liver-specific aspartateS/glutamate transporter encoding gene for citrin protein, located on 7q21.3 locus." (PMID 41586257, 2025). "In this study, the four most common recessive genes of metabolism disorders were identified (> 1/60), including the SRD5A2 gene (5-alpha reductase deficiency), ATP7B gene (Wilson disease), PAH gene (Phenylketonuria), and SLC25A13 gene (Citrin deficiency)." (PMID 40447697, 2025). "Citrin deficiency (citrullinemia type II), stemming from mutations in the SLC25A13 gene encoding for citrin, impairs aspartate-glutamate exchange in the mitochondria of liver cells." (PMID 39583614, 2024). "Here, we have provided important mechanistic insights for most of these questions and new insights into the molecular cause of citrin deficiency, caused by the dysfunction of SLC25A13." (PMID 39419476, 2024). "Clinically, 20 patients were diagnosed with citrin deficiency; however, genetic testing detected a heterozygous mutation in the SLC25A13 gene (nine via Sanger sequencing and 11 via panel-based NGS)." (PMID 38510075, 2024). "SLC25A13 gene mutations are responsible for diseases related to citrin deficiency (CD), such as neonatal intrahepatic cholestasis caused by citrin deficiency and adult-onset type II citrullinemia (CTLN2)." (PMID 37242166, 2023). "Citrin deficiency is an autosomal recessive disorder caused by pathological variants in the SLC25A13 gene." (PMID 36927542, 2023). "The patient was genetically diagnosed as citrin deficiency with a mutation in the SLC25A13 gene via newborn screening for metabolic disorders." (PMID 35244055, 2022). "NICCD is a type of citrin deficiency that is a hereditary IEM caused by SLC25A13 mutations and manifests as neonatal intrahepatic cholestasis." (PMID 35664874, 2022). "Citrin deficiency is inherited in an autosomal recessive manner and is caused by pathogenic variants of the SLC25A13 gene, which encodes the mitochondrial aspartate/glutamate carrier isoform 2 (AGC2), also called citrin." (PMID 35725541, 2022). "A fat-enriched and carbohydrate-restricted (normal protein) diet is the therapy for SLC25A13 related citrin deficiency." (PMID 36079864, 2022). "Diagnosis of citrin deficiency requires a high level of clinical suspicion and is confirmed by identifying pathogenic mutations in the SLC25A13 gene." (PMID 34026689, 2021). "As a subtype of citrin deficiency (CD), it is an autosomal recessive disease related to the SLC25A13 mutation on chromosome 7q21.3." (PMID 33817322, 2021). "Citrin deficiency is an autosomal recessive disorder caused by mutations of the SLC25A13 gene on chromosome 7q21.3." (PMID 31607264, 2019). "The carrying rate of pathogenic variants of SLC25A13 in Guangzhou population is 1/40 and the estimated prevalence of Citrin deficiency is 1/6400." (PMID 33072985, 2019). "Citrin deficiency is an autosomal recessive disorder caused by mutations in the SLC25A13 (solute carrier family 25 member 13) gene." (PMID 30642297, 2019). "Materials and Methods: The mutations for the SLC25A13 gene of citrin deficiency, were analyzed in newborns who demonstrated an inconclusive primary screening result." (PMID 33072985, 2019). "Neonatal Intrahepatic Cholestasis caused by Citrin Deficiency (NICCD) arises from biallelic SLC25A13 mutations, and SLC25A13 analysis provides reliable evidences for NICCD definite diagnosis." (PMID 29152073, 2017). "This large transposon insertion has previously been described in SLC25A13 causing citrin deficiency." (PMID 28187749, 2017).
citrin deficiency (continued). "Human citrin deficiency (CD) is an autosomal recessive disease entity caused by SLC25A13 gene mutations." (PMID 24586645, 2014). "SLC25A13 analysis has provided reliable evidences for the definitive diagnosis of citrin deficiency (CD) in the past decade." (PMID 24586645, 2014). "Mutations in the SLC25A13 gene lead to metabolic diseases caused by an impaired urea cycle, collectively called citrin deficiency." (PMID 25410934, 2014). "A rapid genetic test for citrin deficiency performed by screening for 11 common mutations of SLC25A13 has been developed, but further validation using a larger scale of dried blood samples is necessary prior to the clinical application of this technique." (PMID 23394329, 2013). "SLC25A13 mutations result in citrin deficiency (CD), and CTLN2 was the firstly-described CD phenotype, which occurs in adolescents or adults and the prognosis is usually not benign." (PMID 24069319, 2013). "Three mutations in the SLC25A13 gene (for citrin deficiency) and one mutation in the SLC22A5 gene (for CUD) were analyzed in newborns who demonstrated an inconclusive primary screening result (with levels between the screening and diagnostic cutoffs)." (PMID 23394329, 2013). "Citrin deficiency (CD) is an autosomal recessive disease caused by SLC25A13 gene mutation." (PMID 37063661, 2023). "In our study, the child with citrin deficiency has a homozygous frameshift mutation in the SLC25A13 gene: c.852_855delTATG (p.Met285ProfsTer2).This mutation may lead to the loss of gene function and belongs to pathogenic variation." (PMID 36927542, 2023). "Mutations in SLC25A13 can cause citrin deficiency, which may result in neonatal intrahepatic cholestasis." (PMID 37790589, 2023). "Citrin deficiency that is caused by biallelic SLC25A13 mutations is an autosomal recessive disease and can present as neonatal intrahepatic cholestasis (NICCD; OMIM, 605814) in infants or as adult-onset citrullinemia type II (CTLN2; OMIM, 603471) in adolescents and adults." (PMID 34026689, 2021). "By contrast, the second isoform of the mitochondrial aspartate/glutamate carrier, AGC2, encoded by the SLC25A13 gene, is mainly expressed in liver and mutations in this gene lead to neonatal intrahepatic cholestasis caused by citrin deficiency (NICCD) and adult-onset type II citrullinemia (CTLN2)." (PMID 31514314, 2019). "Citrin deficiency (CD) is a Mendelian disease due to biallelic mutations of SLC25A13 gene." (PMID 27405544, 2016). "Citrin deficiency (CD) is a Mendelian disease entity due to biallelic mutations of SLC25A13 gene." (PMID 27405544, 2016). "Biallelic mutations of the SLC25A13 gene result in citrin deficiency (CD) in humans." (PMID 25216257, 2014). "In addition, the MMCA assay could efficiently identify prevalent SLC25A13 mutations, which would be a good test for preconception carrier screening and contribute to the prenatal counseling of citrin deficiency." (PMID 34026689, 2021). "These new findings enriched the variant spectrum of the SLC25A13 gene and provided a reference for the definite diagnosis of NICCD, which can also be a valuable method for the epidemiological investigation of citrin deficiency in special populations." (PMID 39872914, 2024). "Neonatal intrahepatic cholestasis caused by citrin deficiency (NICCD) is the major pediatric CD phenotype, and its definite diagnosis relies on SLC25A13 genetic analysis." (PMID 27405544, 2016). "Citrin deficiency (CD) is an inborn error of metabolism and a secondary urea cycle disorder caused by pathogenic variants of the SLC25A13 gene (OMIM #603859), encoding the mitochondrial aspartate/glutamate carrier 2 (AGC2), also called citrin." (PMID 40145619, 2025). "Human citrin deficiency is an autosomal recessive disease due to dysfunction of citrin, the liver-type calcium-stimulated aspartate-glutamate carrier isoform 2 (AGC2) encoded by the SLC25A13 gene." (PMID 27127784, 2016).
citrin deficiency (continued). "Although, a series of clinical manifestations and biochemical findings have been observed and described in patients with citrin deficiency, none of these features are pathognomonic, and SLC25A13 genetic analysis has been proposed as an accurate diagnostic tool for citrin deficiency." (PMID 34026689, 2021). "Studies have shown that patients who develop citrin deficiency or adult-onset type II citrullinemia due to SLC25A13 gene mutation are prone to steatosis, NASH and even hepatocellular carcinoma; therefore, the role of SLC25A13 in metabolic diseases may be worthy of further study." (PMID 39850557, 2024).
adult-onset type II citrullinemia (33 papers, 2012 to 2025). "For instance, type II citrullinemia, primarily allotted to the start-lost variant rs541276426 in SLC25A13, had clinical incidences that were 90-fold lower than predicted by our model." (PMID 34078906, 2021). "Variants in the SLC25A13 gene encoding AGC2 induce adult onset type II citrullinemia, due to the specific loss of liver argininosuccinate synthetase." (PMID 33426505, 2020). "Mutations in the Slc25a13 gene result in citrullinemia type II, which is characterized by neuropsychiatric symptoms including abnormal behaviors, loss of memory, seizures and coma." (PMID 30537945, 2018). "The term CITRIN was designated in 1999 to stand for the protein product encoded by SLC25A13 gene, which was localized to chromosome 7q21.3 and cloned as the causative gene for Adult-onset Citrullinemia Type 2 (CTLN2, OMIM #603471)." (PMID 24069319, 2013). "AGC2 dysfunction by mutations in the SLC25A13 gene leads to citrullinemia type II." (PMID 32793632, 2020). "Patient V‐1 was affected by citrullinemia type II, neonate‐onset (aka NICCD, MIM #605814), caused by the compound heterozygous variants in SLC25A13 gene, SLC25A13: c.852_855delTATG/ c.1021 + 1G>A, inherited from the asymptomatic parents, respectively." (PMID 33611823, 2021). "The second AGC isoform (AGC2, SLC25A13) is associated with neonatal and adult-onset type II citrullinemia, an autosomal recessive disease caused by a liver-specific loss of argininosuccinate synthetase activity." (PMID 28620281, 2017). "Similarly, variability profiles of the aspartate transporter SLC25A13 recapitulated increased prevalence of type II citrullinemia (OMIM 605814) in East Asians, with aggregated loss-of-function frequencies of 0.8%, corresponding to 1 in 15,625 homozygous East Asian carriers." (PMID 31679053, 2019).
citrullinemia (17 papers, 2010 to 2025). Citrullinemia is an autosomal recessively inherited disorder of urea cycle metabolism and ammonia detoxification characterized by elevated concentrations of serum citrulline and ammonia. "As a result, variants of SLC25A13 can lead to metabolic abnormalities such as citrullinemia, hyperammonemia, hypoglycemia, and hyperlipidemia." (PMID 37063661, 2023). "Cholestasis, citrullinemia, argininemia, and neonatal steatosis were detected in this young infant, and the genetic study revealed the SLC25A13 mutation 851–854 del and 615 + 5G > A. The final diagnosis was NICCD." (PMID 34684069, 2021). "At the almost same time, we also diagnosed with DNA diagnosis that the transient citrullinemia patients of Dr. Ohura also had mutations in SLC25A13." (PMID 32722104, 2020). "In all patients with citrullinemia, the most common mutation was c.IVS16ins3Kb of SLC25A13 gene, accounting for 25.0% of mutational alleles and 50.0% of patients, followed by c.852_855delTATG of SLC25A13 gene (18.8% and 37.5%)." (PMID 31737040, 2019). "Of eight patients with Citrullinemia, seven were confirmed CTLN2 caused by mutations in SLC25A13 (MIM* 603859) gene, and only one cittrullinemia I (CTLN 1; MIM# 215700) caused by mutations in ASS1 (MIM* 603470) gene." (PMID 31737040, 2019). "Additionally, two cases (5.0% of the total abnormalities) of citrullinemia were caused by mutations in SLC25A13." (PMID 41329681, 2025). "In the present study, we performed genetic analysis of nine Chinese infants with citrullinemia, and identified homozygous or compound heterozygous mutations of ASS1 and SLC25A13." (PMID 35309121, 2022). "For example, using established disease loci as a positive control, we highlight the examples of types I and II citrullinemia (MIM#215700, #603859), which are caused by mutations in ASS1 and SLC25A13, respectively." (PMID 27453504, 2016). "Defects in these genes are associated with various clinical conditions including obesity, type-2 diabetes (ADRB2), citrullinemia (SLC25A13), Tangier disease and systemic amyloidosis (APOA1)." (PMID 26030409, 2015). "Mutation(s) of human SLC25A13 gene encoding a mitochondrial aspartate/glutamate carrier isoform 2 (AGC2), can lead to AGC2 deficiency, resulting in NICCD and an adult-onset fatal disease namely citrullinemia type II (CTLN2)." (PMID 23067347, 2012).
intrahepatic cholestasis (12 papers, 2012 to 2025). A cholestasis characterized by impairment of the bile flow caused by obstruction located in the liver. "Therefore, we suggest that SLC25A13 should be compulsory after CFTR, which causes the most common AR genetic disorder in white population, in every panel for children with intrahepatic cholestasis." (PMID 27706244, 2016).
hepatocellular carcinoma (6 papers, 2019 to 2025). A malignant tumor that arises from hepatocytes. "Germline variants in the SLC25A13 gene have been linked to hepatocellular carcinoma in Asian populations, indicating that the malate-aspartate transport system may play a role in the development of tumors." (PMID 40242210, 2025). "As a tumour suppressor, FOXA2 could be responsible for SLC25A13 high expression levels in liver and its downregulation in hepatocellular carcinoma (HCC)." (PMID 30995827, 2019).
Hepatic steatosis (5 papers, 2019 to 2025). Steatosis is a term used to denote lipid accumulation within hepatocytes. "We summarized the clinical characteristics of 19 CTLN2 patients compared with 25 fatty liver patients without SLC25A13 gene mutation." (PMID 37242166, 2023). "Our data reveal that TNF’s disruptive hepatic mitochondrial FFA β-oxidation is aggravated in Slc25a13-/- mice, leading to accelerated circulatory FFA accumulation and hepatic steatosis." (PMID 41132685, 2025).